PTPRZ1 (protein tyrosine phosphatase receptor type Z1)
Description:
Protein tyrosine phosphatase that negatively regulates oligodendrocyte precursor proliferation in the embryonic spinal cord. Required for normal differentiation of the precursor cells into mature, fully myelinating oligodendrocytes. May play a role in protecting oligondendrocytes against apoptosis. May play a role in the establishment of contextual memory, probably via the dephosphorylation of proteins that are part of important signaling cascades (By similarity).
Synonyms: PTPRZ; PTPZ; PTP18; RPTPB; phosphacan; HPTPZ; HPTPzeta; PTP-ZETA; R-PTP-zeta-2; RPTPbeta
Tractability: Small molecule: a structure with a bound ligand is known; it has a high-quality binding pocket; it belongs to a druggable protein family. Antibody: UniProt places it where antibodies can reach, with high confidence; its Gene Ontology location is reachable by antibodies, with high confidence; UniProt predicts a signal peptide or a membrane-spanning region. PROTAC: its protein half-life has been measured; a small molecule that binds it is known.
Target class: Enzyme; Hydrolase
Gene: Protein-coding gene on chromosome 7 (121,873,089 to 122,062,037, forward strand). Ensembl gene ENSG00000106278.
Subcellular location: Cell membrane (Isoform 1); Secreted; Secreted (Isoform 2)
Subcellular location (Human Protein Atlas): Cytosol; Vesicles; Predicted to be secreted
Pathways (Reactome):
Immune System: Other interleukin signaling
Signal Transduction: MDK and PTN in ALK signaling
Gene Ontology:
Molecular function: integrin binding; protein binding; protein tyrosine phosphatase activity; transmembrane receptor protein tyrosine phosphatase activity
Biological process: central nervous system development; learning or memory; negative regulation of neuron apoptotic process; neuron projection development; oligodendrocyte differentiation; peptidyl-tyrosine dephosphorylation; positive regulation of oligodendrocyte differentiation; protein dephosphorylation; regulation of myelination; regulation of oligodendrocyte progenitor proliferation; signal transduction
Cellular component: plasma membrane; extracellular region
Genetic constraint (gnomAD): Loss-of-function variants: 77 observed, 187.3 expected, observed/expected ratio (o/e) 0.41, 90% interval 0.34 to 0.5. The upper end of that interval is the gene's LOEUF score, 0.5, which puts it in group 2 of 6, group 1 being the genes least tolerant of losing a copy. Missense variants: 2,421 observed, 2,657.6 expected, observed/expected ratio (o/e) 0.91, 90% interval 0.88 to 0.94. Synonymous variants: 885 observed, 971.87 expected, observed/expected ratio (o/e) 0.91, 90% interval 0.86 to 0.96.
Homologues: Orthologues: chimpanzee PTPRZ1 (99% identical), macaque PTPRZ1 (98% identical), pig PTPRZ1 (86% identical), rabbit PTPRZ1 (85% identical), rat Ptprz1 (82% identical), mouse Ptprz1 (82% identical), dog PTPRZ1 (59% identical), guinea pig PTPRZ1 (55% identical), tropical clawed frog ptprz1 (53% identical), zebrafish ptprz1a (36% identical), zebrafish ptprz1b (30% identical). Paralogues in human: PTPRG (31% identical), PTPRF (19% identical), PTPRD (19% identical), PTPRS (18% identical), PTPRM (15% identical), PTPRK (14% identical), PTPRT (14% identical), PTPRU (14% identical), PTPRC (11% identical), PTPRB (11% identical), PTPRA (11% identical), PTPRE (10% identical), and 23 more.
Diseases named in the same sentence as PTPRZ1 in open-access papers:
PTPRZ1 is named in the same sentence as 77 diseases in open-access papers, as found by Europe PMC text mining. Sharing a sentence is not in itself a finding about the gene and the disease. The quoted sentences say what the papers report.
glioblastoma (73 papers, 2010 to 2026). The most malignant astrocytic tumor (WHO grade IV). "PTPRZ1 is a clinically relevant antibody in glioblastoma associated with stemness, and telomerase (TRT) is a major oncogene, whose promoter is mutated in approximately 80% of glioblastoma patients and is associated with tumor progression." (PMID 41208963, 2025). "To evaluate the extent of PTPRZ1 association with gliomas, we first examined its expression at transcript and protein levels in human glioblastoma tissues." (PMID 39893177, 2025). "Noteworthy, IL-34 selectively bound PTPRZ1 in CSF-1R-deficient U251 human glioblastoma cells and led to an increase in the tyrosine phosphorylation of FAK and suppression of cell motility." (PMID 29796177, 2018). "A recent study on primary human glioblastomas suggested a close association between PTPRZ1 (human PTPRZ) expression and cancer stemness." (PMID 28717188, 2017). "In addition, a previous study revealed that tumor-associated macrophages secrete PTN, which is tumor-promoting and positively associated with PTPRZ1 expression and stemness of glioblastoma cells." (PMID 39893177, 2025). "PTPRZ1 is preferentially expressed in the central nervous system and has been suggested to have a close association with cancer stemness in human glioblastoma, as demonstrated by altering the expression of stem cell transcription factors following knockdown of PTPRZ1." (PMID 39518121, 2024). "Also, in glioblastoma cells PTN has been shown to cause a dephosphorylation of PTPRZ1, which is normally constituently active, resulting in an increase in phosphorylated β-catenin." (PMID 35250852, 2022). "Indeed, the fusion genes PTPRZ1-Met can be present on the cargo of EVs released by glioblastoma cell lines and transferred to other glioblastoma cells, causing a more aggressive phenotype in the recipient cells." (PMID 32384712, 2020). "In addition, PTPRZ1-MET fusions were found in secondary glioblastoma, where they can co-occur with MET exon 14 skipping mutations." (PMID 31776899, 2020). "PTPRZ1 is overexpressed in a number of tumors and has been implicated in glioblastoma pathogenesis." (PMID 20224786, 2010). "Moreover, altered Ptprz1 expression is associated with schizophrenia and glioblastoma." (PMID 41942273, 2026). "However, it is interesting that glioblastomas expressing PTPRZ1-MET often also express METΔEx14 splice variant, suggesting that MET activation in these tumors may be complex." (PMID 40361420, 2025). "Protein tyrosine phosphatase receptor type Z1 (PTPRZ1), is a clinically targetable glioblastoma antigen associated with glioblastoma cell stemness." (PMID 39893177, 2025). "PTPRZ1-derived ligands were found across examined primary glioblastoma cell lines, and PTPRZ11814-1822, in particular, was among the overlapping PTPRZ1-derived ligands." (PMID 39893177, 2025). "Single-cell sequencing of primary brain tumors shows PTPRZ1 overexpression in malignant cells, especially in glioblastoma stem cells (GSCs) and astrocyte-like cells." (PMID 39893177, 2025). "To evaluate PTPRZ1 antigen levels required for TCR-T efficacy, we next assessed the expression levels of PTPRZ1 in our panel of generated primary spheroid glioblastoma cell lines." (PMID 39893177, 2025). "Whereas the mechanistic relevance of PTPRZ1 in glioblastoma remains elusive, its functions and contributions to disease malignancy are well-demonstrated, ranging from cancer cell proliferation and stemness to angiogenesis and therapy resistance." (PMID 39893177, 2025). "In TCGA bulk RNA sequencing (RNA-seq) data, PTPRZ1 was significantly upregulated in glioblastoma compared to adjacent normal." (PMID 39893177, 2025). "Recent studies have employed PTPRZ1 along with other markers to define glioblastoma stem cells (GSC) in single-cell transcriptomic and flow cytometric analyses." (PMID 39893177, 2025).
glioblastoma (continued). "In these engineered primary glioblastoma cells, we found that a reduction of mean PTPRZ1 expression of approximately 60% abolished TCR-T cytotoxicity." (PMID 39893177, 2025). "Apart from PTPRZ1 upregulation in glioblastoma, we also found robust overexpression of PTPRZ1 in IDH-mutant gliomas." (PMID 39893177, 2025). "As previously shown, PTPRZ1 is higher expressed in AC-like and OPC-like cells and associated with glioblastoma stemness." (PMID 39893177, 2025). "Multimer-sorted PTPRZ11814-1822-T cells demonstrated cytotoxicity against HLA-A*02+ glioblastoma cell lines with PTPRZ1 expression." (PMID 39893177, 2025). "Benchmarking cytotoxicity, we cocultured PTPRZ1-TCR-T with primary HLA-A*02+ glioblastoma cell lines, D170_44 and P3, and found comparable cytotoxicities." (PMID 39893177, 2025). "Again, both CD8+ and CD4+ PTPRZ1-TCR-T cells were activated by the primary glioblastoma cell line D170_44." (PMID 39893177, 2025). "Here, we identify a therapeutic HLA-A*02-restricted PTPRZ1-reactive TCR retrieved from a vaccinated glioblastoma patient." (PMID 39893177, 2025). "These inhibitors have shown efficacy in vitro against glioblastoma with PTPRZ1-MET rearrangement; however, their clinical efficacy in glioblastoma is currently unclear, with ongoing clinical trials investigating their potential." (PMID 39411129, 2024). "Disrupting the PTN receptor PTPRZ1 has been shown to inhibit the growth of glioblastoma stem cells (GSCs)." (PMID 39403379, 2024). "PTPRZ1–MET fusions connecting the first one, two, three or eight exons of the receptor tyrosine phosphatase PTPRZ1 with exon 2 of MET just before the open reading frame (ORF) start codon have been previously reported in glioblastoma." (PMID 38254850, 2024). "This activated Fyn and AKT signaling in glioblastoma stem cells via its receptor PTPRZ1, thereby promoting tumor growth as confirmed by studies." (PMID 39285301, 2024). "Tumor-associated macrophages secrete abundant pleiotrophin (PTN) to stimulate glioma stem cells via their receptor PTPRZ1, thereby promoting malignant growth of glioblastoma through PTN-PTPRZ1 paracrine signaling." (PMID 38383423, 2024). "PTPRZ1 is best known for its role in axonal guidance and contributions to stem cell properties in glioblastoma, and blocks oligodendrocyte differentiation." (PMID 39518121, 2024). "The mRNA expression analysis also showed that the basal expression of both MET and ST7 are very low in the glioblastoma cases, in contrast to the very high basal expression of PTPRZ1." (PMID 38254850, 2024). "Using the yeast two-hybrid system, the Src TK family member Fyn was found to interact with the intracellular domain of PTPRZ1, while more recently, this interaction was verified in glioblastoma (GBM) stem cells." (PMID 37175798, 2023). "PTPRZ1 has been found over-expressed in various tumors such as lung cancer, cervical cancer, hepatocarcinoma, renal cancer, and glioblastoma." (PMID 36874110, 2023). "PTPRZ1 (Protein tyrosine phosphatase receptor type Z1) –Met (PTPRZ1-Met) in EV cargo in glioblastoma cells transferred to other cells created an aggressive phenotype." (PMID 35159299, 2022). "The presence of PTPRZ1 (Protein Tyrosine Phosphatase Receptor Type Z1) –Met (PTPRZ1-Met) in EV cargo in glioblastoma cells led in an aggressive phenotype when transferred to corresponding cells." (PMID 36059497, 2022). "Together, these results supported the PTPRZ1-positive oRG-like glioblastoma cells as being one of several GSC cell types and showed their invasive nature and involvement in tumor propagation." (PMID 34948008, 2021). "The oRG network was strongly recapitulated in glioblastoma, with the same hub genes such as PTPRZ1 and HOPX, and with confirmed expression at the protein level." (PMID 34948008, 2021). "The oRG-like population in glioblastoma cells was further enriched using FACS PTPRZ1-positive selection and re-analyzed by scRNA-seq." (PMID 34948008, 2021).
glioblastoma (continued). "In order to relate these findings to invasive behaviour in glioblastoma, an in vitro invasion assay used tumour samples treated with either control shRNAs, PTPRZ1 shRNAs, or Rock inhibitor." (PMID 34948008, 2021). "Consistently, both astrocytes and meningioma cells in coculture samples increased expression of the PTPRZ1 ligand PTN over time, which activates PTPRZ1 to promote glioblastoma stem cell renewal and tumor growth." (PMID 32968068, 2020). "IL-34 binds to the extracellular domain of PTPRZ1 to stimulate the phosphorylation of paxillin and focal adhesion kinase, which influences the growth and migration of glioblastoma cells." (PMID 31727934, 2019). "Chromosome 7 is usually disrupted in many cancers, here we detected the amplification of several genes already implicated in glioblastoma such as: EGFR, SEPT14, NAMPT, NRCAM, AAS and PTPRZ1." (PMID 29844869, 2018). "PTPRZ1 was previously reported to be upregulated in glioblastoma compared with normal brain at both the mRNA and protein levels." (PMID 28924174, 2017). "As NAZ2329 preferentially inhibits both PTPRG and PTPRZ1, NAZ2329 is expected to be superior to sole inhibitors of PTPRZ or PTPRG for inhibiting the malignant properties of glioblastoma cells." (PMID 28717188, 2017). "Out of the seven PTPs, all but PTPRZ1 had significantly lower expression levels in glioblastoma tumors as compared to lower grade glioma samples, in agreement with our qPCR findings." (PMID 27586084, 2016). "PTPRZ1 knock-down in glioblastoma cell lines reduced cell migration and tumor growth, and PTPRZ overexpression enhanced cell migration." (PMID 25238264, 2014). "We show that PTPRZ1 knock-down in E98 glioblastoma and E434 oligodendroglioma cells results in impaired growth and motility in vitro and reduced tumor growth in vivo, also in diffuse infiltrative tumor areas." (PMID 25238264, 2014). "Inhibition of PTPRZ1 expression with small interfering RNA suppresses glioblastoma growth in vitro and in vivo." (PMID 25360666, 2014). "Further evidence for the importance of PTPRZ1 in glioblastoma is provided by the finding that down regulation of PTPRZ1 by siRNA suppresses glioblastoma growth in vitro and in vivo." (PMID 20224786, 2010). "Here, we perform a comprehensive multimodal assessment of PTPRZ1 in glioblastoma, demonstrate that it is a highly attractive immunotherapeutic target, and develop an off-the-shelf TCR-T therapy which is, in principle, applicable for all HLA-A*02+ glioma patients." (PMID 39893177, 2025). "Additionally, we grouped TCGA glioblastoma tumors according to dominant glioblastoma cell states, and concluded again that PTPRZ1 positively correlated with an AC-like state and GSC." (PMID 39893177, 2025). "Here authors identify a T cell receptor in a vaccinated glioblastoma patient that specifically recognizes the glioblastoma stem cell antigen PTPRZ1 and utilise it in T cell receptor-engineered T (TCR-T) cell therapy, resulting in efficient tumour cell killing in vitro and in a mouse model." (PMID 39893177, 2025). "Examples of this include the PTPRZ1-MET fusion seen in a subset of pediatric glioblastomas." (PMID 40361420, 2025). "The glioblastoma cell cluster expressed high levels of PTPRZ1." (PMID 39893177, 2025). "Additionally, pleiotrophin (PTN) secreted by CD163+ MDMs binds to protein tyrosine phosphatase receptor type Z1 (PTPRZ1) on the surface of glioblastoma stem cells (GSCs)." (PMID 40800581, 2025). "In a study conducted by Shi and colleagues in 2017, it was reported that GAMs secrete abundant pleiotrophin (PTN), which stimulates glioma stem cells (GSCs) through its receptor PTPRZ1, thereby promoting malignant growth of glioblastoma (GBM) through PTN–PTPRZ1 paracrine signaling." (PMID 38732975, 2024). "Additionally, juxtacrine secreted from glioblastoma TAMs activates PTPRZ1 signaling in glioblastoma CSCs, fostering tumor growth." (PMID 38460015, 2024).
glioblastoma (continued). "All of our results suggest that blocking GPM6A or PTPRZ1 could represent an interesting approach in the treatment of glioblastoma, since it would simultaneously target proliferation, invasion, and radioresistance." (PMID 35883571, 2022). "In contrast, less prevalent actionable fusions exhibited tumour type specificity including CCDC6-RET fusions in thyroid and lung cancer, FGFR2-BICC1 in cholangiocarcinoma, PTPRZ1-MET in glioblastoma, EIF3E-RSPO2 and PTPRK-RSPO3 in colorectal cancer and KIF5B-RET in NSCLC as previously reported." (PMID 35984852, 2022). "Notably, various cell line studies and mouse studies have shown that inhibiting PTPRZ1, for example by shRNAs, can slow glioblastoma tumor growth and migration." (PMID 35338126, 2022). "Glioblastoma tumor stem cells (CSCs) have large amounts of its receptor, PTPRZ1, which activate a series of signaling pathways that produce CSCs and maintain their malignant behavior, promoting tumor growth and progression and leading to increased mortality in patients." (PMID 36568388, 2022). "Our results suggest that blocking GPM6A or PTPRZ1 could represent an interesting approach in the treatment of glioblastoma since it would simultaneously target proliferation, invasion, and radioresistance." (PMID 35883571, 2022). "PTPRZ1 and its ligand, PTN, have been previously identified as necessary for tumour invasion and viability and linked with the known effects of the Rho/Rho-kinase signalling pathway in glioblastoma." (PMID 34948008, 2021). "Additionally, TAMs are also known to secrete pleiotrophin (PTN) that promotes glioblastoma tumor growth and stem cell maintenance via protein tyrosine phosphatase receptor type Z1 (PTPRZ1) signaling." (PMID 34503065, 2021). "Moreover, downregulating PTPRZ1 expression in glioblastoma multiforme (GBM) cells produced a decrease in tumour migration and proliferation." (PMID 30497491, 2018). "Moreover, a monoclonal antibody to PTPRZ1 has been shown to delay tumor growth in a glioblastoma model." (PMID 20224786, 2010). "Moreover, PTPRZ1 is overexpressed in a number of tumors, including hepatocarcinoma, renal carcinoma, and glioblastoma." (PMID 20224786, 2010). "In addition, PTPRZ1 and its ligand pleiotrophin are overexpressed in human glioblastoma and there is substantial evidence that these proteins play an important role in the pathogenesis of this cancer." (PMID 20224786, 2010). "PTPRZ1 plays a key role in cell migration, and is a potential tumor target in glioblastoma multiforme (GBM)." (PMID 32231047, 2020). "Three of these genes (PTPRZ1, PTEN, PTPRT) encode PTPs with C-terminal PDZ binding motifs and mapping of the interacting PDZ domain-containing proteins may be of relevance for glioblastoma etiology." (PMID 29439552, 2018). "In human glioblastoma, IL-6 levels are endogenously lower in patients who achieve histological or radiographic responses to ICI, and ICI-resistant glioblastoma has elevated stem cell markers (SOX2, SOX4, SOX13, PTPRZ1), which can be driven by IL-621,58." (PMID 40161763, 2025). "In a paired glioma and stromal cell scRNA-seq dataset (n(glioblastoma)=16, n(IDH-mut glioma)=3, and n(pediatric high-grade glioma)=1), we independently validated malignant cell-type specificity of PTPRZ1 expression." (PMID 39893177, 2025). "Protein tyrosine phosphatase receptor type Z1 (PTPRZ1) and GPM6A are essential for the formation of glioblastoma (GB) stem cells (GBSC) spheres." (PMID 39957375, 2025). "PTPRZ1-TCR-T maintain stem cell memory phenotype in vitro and in vivo and lyse all examined HLA-A*02+ primary glioblastoma cell lines with a preference for GSCs and astrocyte-like cells." (PMID 39893177, 2025). "Primary HLA-A*02+ glioblastoma cell lines led to activation of CD8+ PTPRZ1-TCR-T at various degrees and additionally activated CD4+ PTPRZ1-TCR-T in a moderate fashion." (PMID 39893177, 2025).